ALDH3A1 (aldehyde dehydrogenase 3 family member A1)
Description:
ALDHs play a major role in the detoxification of alcohol-derived acetaldehyde (Probable). They are involved in the metabolism of corticosteroids, biogenic amines, neurotransmitters, and lipid peroxidation (Probable). Oxidizes medium and long chain aldehydes into non-toxic fatty acids. Preferentially oxidizes aromatic aldehyde substrates. Comprises about 50 percent of corneal epithelial soluble proteins (By similarity). May play a role in preventing corneal damage caused by ultraviolet light (By similarity).
Synonyms: ALDH3; ALDHIII
Tractability: Small molecule: a structure with a bound ligand is known; a high-quality ligand is known; it has a high-quality binding pocket; it belongs to a druggable protein family. Antibody: its Gene Ontology location is reachable by antibodies, with high confidence. PROTAC: ubiquitination databases record sites on it; a small molecule that binds it is known.
Target class: Enzyme; Oxidoreductase
Safety:
Unwanted effects reported when the protein is acted on. In parentheses: how it was acted on, where the effect was seen, and who reports it.
anemia and leukopenia (source: ClinPGx)
Gene: Protein-coding gene on chromosome 17 (19,737,984 to 19,748,943, reverse strand). Ensembl gene ENSG00000108602.
Subcellular location: Cytoplasm
Subcellular location (Human Protein Atlas): Cytosol; Plasma membrane; Nucleoplasm; Vesicles
Pathways (Reactome):
Metabolism: Phase I - Functionalization of compounds
Gene Ontology:
Molecular function: aldehyde dehydrogenase (NAD+) activity; aldehyde dehydrogenase [NAD(P)+] activity; benzaldehyde dehydrogenase (NAD+) activity; protein binding; 3-chloroallyl aldehyde dehydrogenase activity; medium-chain fatty aldehyde dehydrogenase (NAD+) activity; oxidoreductase activity; oxidoreductase activity, acting on the aldehyde or oxo group of donors, NAD or NADP as acceptor
Biological process: aldehyde metabolic process; xenobiotic metabolic process
Cellular component: cytosol; endoplasmic reticulum; extracellular region; mucus layer; cytoplasm; membrane
Genetic constraint (gnomAD): Loss-of-function variants: 47 observed, 48.12 expected, observed/expected ratio (o/e) 0.98, 90% interval 0.77 to 1.25. The upper end of that interval is the gene's LOEUF score, 1.25, which puts it in group 5 of 6, group 1 being the genes least tolerant of losing a copy. Missense variants: 576 observed, 593.62 expected, observed/expected ratio (o/e) 0.97, 90% interval 0.9 to 1.04. Synonymous variants: 258 observed, 245.61 expected, observed/expected ratio (o/e) 1.05, 90% interval 0.95 to 1.16.
Homologues: Orthologues: chimpanzee ALDH3A1 (99% identical), macaque ALDH3A1 (90% identical), guinea pig ALDH3A1 (88% identical), dog ALDH3A1 (87% identical), pig ALDH3A1 (87% identical), rat Aldh3a1 (82% identical), mouse Aldh3a1 (80% identical), zebrafish aldh3a2b (59% identical), zebrafish aldh3a2a (57% identical), Caenorhabditis elegans alh-4 (49% identical), Caenorhabditis elegans alh-5 (48% identical), tropical clawed frog aldh3b1 (44% identical), and 7 more. Paralogues in human: ALDH3A2 (66% identical), ALDH3B1 (53% identical), ALDH3B2 (42% identical), ALDH1A3 (28% identical), ALDH1A1 (27% identical), ALDH1A2 (27% identical), ALDH9A1 (27% identical), ALDH1B1 (26% identical), ALDH2 (26% identical), ALDH1L2 (26% identical), ALDH1L1 (25% identical), ALDH8A1 (24% identical), and 5 more.
Diseases named in the same sentence as ALDH3A1 in open-access papers:
ALDH3A1 is named in the same sentence as 81 diseases in open-access papers, as found by Europe PMC text mining. Sharing a sentence is not in itself a finding about the gene and the disease. The quoted sentences say what the papers report.
lung carcinoma (34 papers, 2008 to 2025). "A recent study has associated ALDH3A1 expression with lung cancer metastasis and poor prognosis, perhaps challenging its presumed role in homeostasis." (PMID 39969205, 2025). "ALDH1A1 and ALDH3A1 were highly expressed in nonsmall cell lung cancer, and knock-down of these ALDH isoforms were associated with in vitro functional changes in the proliferation and motility of these cells." (PMID 23484127, 2013). "In this study, we have used microarray analysis to assess global changes in gene expression that result from the knock-down of ALDH1A1 and ALDH3A1 in lung cancer cell line in order to gain insight into the underlying mechanisms that lead to up regulation of these two isozymes in some cancers." (PMID 19025616, 2008). "Specifically, they found ALDH3A1 overexpression enhanced PD-L1 output in tumor cells, and ALDH3A1 expression correlated with PD-L1 expression in melanoma and lung cancer patient specimens." (PMID 39796106, 2024). "ALDH3A1 is an aldehyde dehydrogenase required for cell migration and the invasion of A549 lung cancer cells." (PMID 39796712, 2024). "This most supported causal variant falls in an enhancer linked to ALDH3A1 by the ABC method (ABCmax = 0.15 in PC-9 cells, derived from human lung carcinoma)." (PMID 37621707, 2023). "Exosomes carrying ALDH3A1 from irradiated lung cancer cells contribute to the motility of recipient cells by accelerating glycolysis." (PMID 37730658, 2023). "A recent study reported that ALDH3A1 promoted the metastasis of lung cancer by accelerating the glycolytic process." (PMID 37730658, 2023). "Aldh3a1 is a putative biomarker of lung cancer, while Gapdh was reported as critical for stem cell therapy of pulmonary hypertensive females." (PMID 37367058, 2023). "mRNA transcripts of GGT-1, LTC4, FECR1, FECR2, miR-106b, ALDOA, ALDH3A1, and other genes in exosomes derived from lung cancer cells act as important regulators by playing an enabling role in promoting the invasion and migration of lung cancer cells." (PMID 34511114, 2021). "Further research showed that exosomes containing the metabolic enzymes ALDOA and ALDH3A1 promoted unirradiated lung cancer cells proliferation by accelerating glycolysis." (PMID 33077737, 2020). "Here, we focused on ALDH3A1 in lung cancer cell lines and melanoma cells, mainly for the availability of patient specimens for these tumors at our institution, the University Hospital of Siena." (PMID 31817719, 2019). "Consistent with our in vitro results, tissues from either lung cancer or melanoma with a high ALDH3A1 H score (i.e., ≥ 4) showed PD-L1 expression higher than 70%, while samples with low ALDH3A1 expression (i.e., ≤ 3) showed low PD-L1 positivity (5–40%)." (PMID 31817719, 2019). "Simultaneous knockout of ALDH1A1 and its isozyme ALDH3A1 in lung cancer cell line NCI-H460 inhibited tumor growth in a xenograft model." (PMID 28978015, 2017). "Other groups have detected ALDH1A1, ALDH1A2, ALDH3A1, and ALDH2A1 in lung cancers which were shown to have an association with chemoresistance." (PMID 24884875, 2014). "Downregulation of ALDH1A1 and ALDH3A1 has been shown to reduce cell growth and motility in lung cancer cells." (PMID 23236365, 2012). "Genes that were highly affected by the knock-down of ALDH1A1 and ALDH3A1 in A549 lung cancer cell line." (PMID 19025616, 2008). "Further analysis on ALDH2, ALDH3a1, FBP1, PGD, TALDO1, and TPI1 as biomarkers on the evolution of IPF patients, their association with PJ infection, and their lung cancer risk could be relevant." (PMID 39997396, 2025). "Notably, PPARγ downregulates ALDHs to suppress lung cancer growth, as seen with arachidonic acid-induced PPARγ activation, which reduces ALDH3A1 and increases lipid peroxidation in A549 cells." (PMID 41304753, 2025).
lung carcinoma (continued). "Overexpression of ALDH3A1 in melanoma and lung cancer not only regulates tumor cell stemness and the process of EMT, but also promotes inflammation through up-regulation of inflammatory factors such as COX2 and PGE2, and enhances the expression of PD-L1 to affect immune escape." (PMID 38099574, 2023). "In the univariate analysis, compared to the low-risk group, AKR1B10, ALDH3A1, CEACAM5, and IDH2 are higher than the high-risk or cancer group, i.e., their upregulation discriminates the low-risk group from the high-risk group as well as the lung cancer group." (PMID 37760474, 2023). "ALDH3A1 was found in lung cancer with abnormal expression, correlated with histologic type 7." (PMID 34234849, 2021). "We conducted a meta-analysis based on The Cancer Genome Atlas and Gene Expression Omnibus data and detected genetic alterations in ALDH1A1, ALDH1A3, or ALDH3A1, 86% of which were gene amplification or mRNA upregulation, in 31% of nonsmall cell lung cancers (NSCLCs)." (PMID 32015486, 2020). "We focused on ALDH1A1, ALDH2 and ALDH3A1 expression among the various isoforms because ALDH1A1 and ALDH3A1 have been shown to be markers of resistance to cyclophosphamide in breast and lung cancer cells and because ALDH2 is a major detoxifying enzyme for reactive aldehydes." (PMID 28881734, 2017). "ALDH3A1 is upregulated in various cancers and is a potential biomarker for lung cancer." (PMID 26580399, 2015). "Three genes (ALDH3A1, VDR and CHKA) are associated both with ATII physiology and lung cancers." (PMID 21489244, 2011). "Therefore, the increased ALDH3A1 expression level in A549 lung cancer cells under combined treatment could counteract oxidative stress and provide resistance against combinatorial treatment." (PMID 33005401, 2020). "ALDH3A1 over-expression can enhance the secretion of PD-L1 in melanoma cells in vitro, and the levels of ALDH3A1 expression are consistently correlated with those of PD-L1 and COX-2 in clinical melanoma and lung cancer samples." (PMID 36199579, 2022). "Collectively, our findings shed light on ALDH3A1 importance for maintaining cancer cell metastasis in LUAD, providing a promising and novel factor for lung cancer treatment." (PMID 34234849, 2021). "ALDH3A1 reduces NAD+ to NADH, hence inducing metabolic liability in NRF2-activated lung cancers." (PMID 39754188, 2025). "Consistent with our findings, it has also been shown by others that overexpression of ALDH1A1 rather than other isoforms (ALDH1A3 and ALDH3A1) increased lung cancer cell transformation and CSC phenotype by activating stem cell drivers Nanog, Oct4, and Sox2." (PMID 28415606, 2017). "Recent evidence suggests that ALDH1 or ALDH3A1, which may be lung tumor stem cell markers or therapeutic targets, are highly expressed in some NSCLC cell lines as well as in patient lung cancer samples." (PMID 27542268, 2016).
breast carcinoma (24 papers, 2009 to 2025). "Collectively, our data support a model whereby melatonin upregulates the expression of BMAL1, which is associated with ALDH3A1, thereby affecting the glycolytic process and ultimately influencing the proliferation of breast cancer cells." (PMID 41228459, 2025). "ALDH3A1 was responsible for drug resistance in breast cancer, but this gene may be associated with drug resistance in EOC." (PMID 30970615, 2019). "The ALDEFLUORTM kit used to isolate CSCs in this study has previously been shown to select cells expressing high levels of ALDH1A1, ALDH3A1, ALDH1A3 and ALDH2 isoforms, which are closely linked to breast cancer stem cells." (PMID 39768151, 2024). "Similar observations were obtained with ALDH3A1+ cells exhibiting high tolerance against three different chemotherapeutics (e.g., doxorubicin, 5-FU and etoposide) in breast cancer Michigan Cancer Foundation-7 (MCF-7) cells." (PMID 33419031, 2021). "Overexpression of ALDH1A1 and ALDH3A1 isoforms have been shown to result in greater inactivation of cyclophosphamide in breast cancer." (PMID 29902974, 2018). "Other ALDH isoforms have been mechanistically associated with metastatic behavior in vitro, including ALDH1A3 in breast cancer, melanoma, pancreatic cancer and brain cancer; ALDH3A1 in prostate cancer and liver cancer; and ALDH7A1 in prostate cancer." (PMID 26445849, 2016). "Microarray analysis in breast cancer cells revealed that knockdown of MTDH led to decreased expression of chemoresistance genes ALDH3A1, MET, HSP90, and HMOX1 and increased expression of proapoptotic genes BNIP3 and TRAIL." (PMID 25993398, 2015). "Similarly, ALDH3A1-overexpressing breast cancer MCF7 cells exhibited increased tolerance to doxorubicin, 5-FU and etoposide." (PMID 39408636, 2024). "However, it was notable in this study that, when expression of ALDH3A1 was examined in breast cancer clinical datasets, high expression was significantly associated with an increased risk of distant metastatic relapse but not with brain-specific relapse." (PMID 30642388, 2019). "Moreover, in ER– breast cancers, elevated expression of either ID2 or ALDH3A1 was associated with reduced distant metastasis-free survival." (PMID 30642388, 2019). "Furthermore, K19-Wnt1/C2mE-KP cells were found to highly express ALDH3A1 mRNA, compared with the sulfasalazine-sensitive mouse breast cancer 4T1 cells." (PMID 30333913, 2018). "In the present study, we demonstrated that genetic variants of the host, such as SNPs of MAP3K1, CYP2B6, UGT1A1, HCN1, ABCB1, and ALDH3A1, may worse the prognosis of HR-positive breast cancer patients, predominantly for premenopausal women." (PMID 28178648, 2017). "In a breast cancer mouse model, CLOCK and BMAL1 in the TME promoted tumorigenesis and metastasis through the upregulation of WNT10A-mediated ALDH3A1 expression in cancer stem cells." (PMID 37524704, 2023). "Examination of the TCGA breast cancer dataset revealed higher levels of ID2 and ALDH3A1 expression in triple-negative (ER–/PR–/HER2–) breast cancers compared with HER2+ and ER+/HER2– breast cancers, and in ER– versus ER+ breast cancers." (PMID 30642388, 2019). "Western blot analysis revealed that in both MCF7 and SKBR3 breast cancer cell lines, the protein expression levels of ALDH3A1 exhibited a negative correlation with BMAL1 expression status." (PMID 41228459, 2025).
prostate carcinoma (11 papers, 2015 to 2025). A carcinoma that arises from epithelial cells of the prostate gland. "For example, ALDH7A1 has been implicated in prostate cancer metastatic activity after left ventricular injection (LVI) of a prostate cancer cell line, while ALDH3A1 has been shown to be associated with metastasis using a mouse tail vein injection model." (PMID 26445849, 2016). "ALDH3A1 was widely investigated in prostate cancer and linked with tumor progression." (PMID 34572930, 2021). "Furthermore, the expression of ALDH3A1 is robustly higher in DU145-derived prostate cancer stem cells, implying that ALDH3A1 associates with prostate tumorigenesis." (PMID 28671577, 2017). "Although ALDH1A1 and ALDH3A1 are most often associated with cancer stem cells, high ALDH4A1 expression has been reported in prostate cancer cells and primary cultures of human prostate cancer." (PMID 39598797, 2024). "In contrast, Le Magnen and colleagues revealed a decreased expression of ALDH3A1 in prostate cancer cells over benign prostate hyperplasia." (PMID 34572930, 2021). "The clinical data suggest an increased level of ALDH3A1 in prostate cancer samples over prostate intraepithelial neoplasia and healthy prostate specimens." (PMID 34572930, 2021). "Yan and co-authors performed immunohistochemical staining in xenografts of prostate cancer stem cells and demonstrated the elevated expression of ALDH3A1 compared to injected monolayer cells." (PMID 34572930, 2021). "ALDH3A1 has been regarded as a therapeutic target in some cancers, like lung, hepatocellular, and prostate carcinomas, based on the evidence that abnormal levels of aldehyde dehydrogenase (ALDH) activity were expressed in human cancer types." (PMID 30935420, 2019). "Although the majority of these studies have focussed on ALDH1A1, ALDH3A1 has been reported to be upregulated in prostate cancer stem cells and in metastatic lesions compared with primary tumours as well as being required for stem cell maintenance and resistance to cytotoxic drugs." (PMID 30642388, 2019). "Previous research studies have reported metabolic enzymes related to glycolysis, including PKM2, ALDOA, and ALDH3A1 carried by EVs that are closely related to the functionality of EVs to promote glycolytic metabolism of recipient cells and bone metastasis of prostate cancer cells." (PMID 40089067, 2025). "Further research could elucidate how exactly ALDH3A1, Latexin, and various other ALDH isoforms are related to each other during prostate cancer progression." (PMID 34572930, 2021).
melanoma (9 papers, 2019 to 2025). A malignant, usually aggressive tumor composed of atypical, neoplastic melanocytes. "Of note, similar to ALDH3A1, in human melanoma ALDH1A1 was shown to associate with cancer stem-like features and therapy resistance." (PMID 31817719, 2019). "ALDH3A1 (Aldehyde Dehydrogenase 3 Family Member A1) contributes significantly to the stemness and immunogenic profile of melanoma and NSCLC (Non-Small Cell Lung Cancer) cells." (PMID 41148223, 2025). "In particular, ALDH3A1 enzyme‐enriched CSCs populations are positively correlated with PD‐L1 expression in melanoma and NSCLC." (PMID 36694633, 2023). "ALDH3A1 has been demonstrated to trigger EMT in melanoma and non-small cell lung cancer cells, while the overexpression of ALDH3A1 enhances PD-L1 expression and lowers monocyte proliferation in peripheral blood." (PMID 35897925, 2022). "Using the H score, we found that 12 out of 13 (92%) lung adenocarcinoma cases and all seven (100%) melanoma cases were positive for ALDH3A1." (PMID 31817719, 2019). "In this study, using melanoma and NSCLC cells, we demonstrate that ALDH3A1 isozyme overexpression and activity is closely associated with a highly aggressive mesenchymal and immunosuppressive profile." (PMID 31817719, 2019). "We show that cells engineered to overexpress the ALDH3A1 enzyme enriched the CSCs population in melanoma and NSCLC cultures, changing their transcriptome." (PMID 31817719, 2019). "Overexpression of ALDH3A1 was found to enhance the secretion of PD-L1 in melanoma cells in vitro." (PMID 41148223, 2025). "Furthermore, there is a consistent correlation between the levels of ALDH3A1 expression and those of PD-L1 and COX-2 in clinical samples, highlighting the significance of ALDH3A1 in the pathophysiology of melanoma." (PMID 41148223, 2025). "The contribution of ALDH3A1 to the stemness and immunogenic status of melanoma and NSCLC cells was evaluated by their ability to grow in 3D forming tumorspheres, and by the expression of markers for stemness, epithelial to mesenchymal transition (EMT), and inflammation." (PMID 31817719, 2019). "To investigate how the varying ALDH3A1 expression levels might affect the carcinogenicity state, we opted to employ tumor cell lines, i.e., NSCLC HCC4006, and melanoma cells WM266-4 and MEL4478D in gain or loss of function studies." (PMID 31817719, 2019). "Furthermore, in specimens from melanoma and NSCLC patients, we investigated the expression of ALDH3A1, PD-L1, and cyclooxygenase-2 (COX-2) by immunohistochemistry." (PMID 31817719, 2019). "To illustrate the purpose of this work, we first discuss the results of the immunohistochemical analysis of ALDH3A1 expression performed on patient specimens taken from lung adenocarcinoma (NSCLC) and skin melanoma (13 patients for NSCLC and seven for melanoma)." (PMID 31817719, 2019). "Furthermore, in tumor specimens from melanoma and NSCLC patients, ALDH3A1 expression was invariably correlated with PD-L1 and the pro-inflammatory marker COX-2." (PMID 31817719, 2019). "ALDH3A1, the ALDH1A subfamily, comprising ALDH1A1, which synthesizes RA from retinaldehyde and, as such, is crucial in regulating RA signaling, has been used as a CSC marker for many solid tumors, including lung and melanoma." (PMID 31817719, 2019). "Some ALDHs, particularly ALDH1A1, ALDH1A3, and ALDH3A1, are widely regarded as markers of stemness in normal tissues (basal skin, bronchial mucosa cells, human cornea, breast, liver), as well as in several solid tumors (non-small-cell lung cancer (NSCLC), melanoma, gastric, breast)." (PMID 31817719, 2019).